IL33 (interleukin 33)
Diseases named in the same sentence as IL33 in open-access papers (continued):
Sharing a sentence is not in itself a finding about the gene and the disease.
ovarian carcinoma (16 papers, 2018 to 2026). A malignant neoplasm originating from the surface ovarian epithelium. "In this context, the present study investigated the serum levels of the sST2 protein in relation to the IL-33/ST2 axis, along with the expression levels of miRNA-29a in ovarian cancer and evaluated the possible association of these parameters with the disease." (PMID 41614943, 2026). "miR-378a-3p decreases interleukin-33 levels and enhances the sensitivity of ovarian cancer cells to cisplatin through targeting MAPK1 and GRB2." (PMID 35791446, 2022). "For instance, IL-33 has been shown to promote ovarian cancer cell growth and metastasis via ERK and JNK signaling pathways." (PMID 31383884, 2019). "In lines with these findings, epithelial ovarian cancer knocked down of IL-33 gene had reduced metastatic potential, while ectopic IL-33 promoted the migratory and invasive capacity." (PMID 30619376, 2018). "Moreover, activation of the IL-33/ST2 axis has been shown to correlate with poor survival outcomes in ovarian cancer patients." (PMID 41614943, 2026). "Similarly, anti-IL-33 antibody treatment has been shown to inhibit glioblastoma and ovarian cancer in experimental models." (PMID 38662248, 2024). "However, IL-33 accelerates ovarian cancer development and metastasis by modulating the activation of the JNK and ERK signalling pathways." (PMID 31889095, 2019). "In addition, IL-33 expression predicted poor prognosis and promoted ovarian cancer cell growth and metastasis through regulating ERK and JNK signaling pathways." (PMID 29568370, 2018). "Underlying mechanisms clarified sST2 might block the ERK and JNK signaling pathways, where IL-33 in return, was regarded as a prognosis markers and targets for ovarian cancers." (PMID 30619376, 2018). "Consistent with this pattern, our study also revealed that serum sST2 concentrations were significantly higher in ovarian cancer patients compared with the control group, suggesting that activation of the IL-33/ST2 axis may contribute to the pathogenesis of ovarian cancer." (PMID 41614943, 2026). "Previously, IL-33 was found to increase tumor cell migration, invasion, and proliferation through regulation of the ERK and JNK signaling pathways in ovarian cancer." (PMID 37056569, 2023). "Still, interleukin-33 (IL-33), another adipokine and part of the IL-1 gene family, has been shown to activate ERK signaling to promote migration and invasion in CAOV3 ovarian cancer cells." (PMID 35565396, 2022). "In a cell line study, it was observed that suppression of the IL-33 gene in epithelial ovarian cancer (EOC) cells reduced their migratory and invasive potential, whereas full-length human IL-33 (fl-hIL-33) promoted the invasive, migratory, and proliferative capacities of EOC cells." (PMID 41614943, 2026). "Among them, IL-33 was considered a pro-cancer cytokine, since the activation pathway of IL-33/ST2 may promote metastases, as observed in some tumors, such as colorectal and ovarian cancer." (PMID 31130612, 2019).
schizophrenia (16 papers, 2016 to 2026). A major psychotic disorder characterized by abnormalities in the perception or expression of reality. "Schizophrenia, a complex neuropsychiatric disorder featuring hallucinations and delusions, shows an association between IL-33 levels and disease progression." (PMID 39925809, 2025). "Serum IL-33 positively correlates with cognitive performance in schizophrenia patients, and elevated serum IL-33 and sST2 levels are linked to improved cognition, whereas IL-33-deficient mice show behavioral deficits." (PMID 39925809, 2025). "There are also some associations between serum IL-33 levels in patients with schizophrenia and their clinical symptoms." (PMID 35743957, 2022). "In addition, the IL-33 gene polymorphism (rs11792633) has been documented to be associated with the development of schizophrenia." (PMID 39925809, 2025). "Thus, an association with acute symptoms in affective disorders and schizophrenia and elevated values of IL-33 has been shown." (PMID 35958655, 2022). "Also, significant association between cognition in patients with schizophrenia and IL-33 levels and the soluble form of IL 33 receptor (sST2) was found." (PMID 35958655, 2022). "Furthermore, the IL-33 gene polymorphism (rs11792633) is associated with the development of schizophrenia." (PMID 34079543, 2021). "Indeed polymorphism of IL-33 is associated with decreased susceptibility to schizophrenia within an Iranian population." (PMID 30515150, 2018). "Increased concentrations of IL-1β, IL-6, IL-10, IL-17, sIL-2R, and IL-33, but also decreased concentrations of TNF-α, were similarly associated with more severe positive symptoms of schizophrenia." (PMID 40364201, 2025). "Schizophrenia patients with higher levels of IL-33 and sST2 have better cognitive performance, especially in verbal memory, fluent attention, and processing speed." (PMID 35743957, 2022). "Some researchers found that the serum levels of IL-33 in first-episode schizophrenia patients were significantly higher than those in relapsing schizophrenia patients and healthy controls." (PMID 35743957, 2022). "The levels of IL-33 and sST2 were positively correlated with the cognitive performance of patients with schizophrenia." (PMID 35974336, 2022). "Three studies measured levels of IL-33 in schizophrenia and two studies focused on patients affected by autism spectrum disorders." (PMID 33810498, 2021). "Three studies measured levels of IL-33 in schizophrenia and two studies focused on patients affected by autism spectrum disorders (ASD)." (PMID 33810498, 2021). "Levels of IL-33 and sST2 are higher in schizophrenia exacerbation in comparison with controls and patients in remission." (PMID 29988422, 2018). "We assume that during CNS damage, neuroinflammation is followed by IL-33 release from necrotic cells and increment of its serum levels in patients with schizophrenia." (PMID 29988422, 2018). "Even though both IL-33 and sST2 levels in chronic schizophrenia patient sera are comparable with those in their control counterparts, serum IL-33 is positively correlated with cognitive performance in patients with schizophrenia." (PMID 34079543, 2021). "Three studies investigated the level of IL-33 in schizophrenia." (PMID 33810498, 2021). "Thus, it is possible that IL-33 production is an attempt to limit inflammation accompanying relapse in schizophrenia." (PMID 29988422, 2018). "The study of two pathways of innate immunity in schizophrenia revealed that the serum levels of IL-33 and its soluble receptor was unaltered in stable disease, but was significantly enhanced in exacerbation and accompanied with hostility and elevation of cardiac troponin levels." (PMID 29988422, 2018). "However, another study found that serum IL-33 levels were positively correlated with positive symptoms of excitement, suspicion/persecution, and hostility, and with general symptoms of anxiety and nervousness during remission of schizophrenia." (PMID 35743957, 2022).
schizophrenia (continued). "Consequently, we wanted to investigate the alterations of innate inflammatory markers Gal-3, IL-33, and sST2 in different stages of schizophrenia and to explore the possible correlation of their serum concentrations with clinical symptomatology and laboratory parameter." (PMID 29988422, 2018). "However, the expression of IL-33 and ST2 in schizophrenia associated brain regions such as prefrontal cortex, basal ganglia, hippocampus, and amygdala may suggest its involvement in disease development." (PMID 30515150, 2018). "In follow-up studies, it will be more interesting if we investigate the downstream targets of IL-33/ST2 signaling and the Treg pathway in schizophrenia." (PMID 35743957, 2022). "There were significant differences in serum IL-33 and ST2 levels in schizophrenia patients compared with healthy patients, especially in men, but not in women." (PMID 35743957, 2022). "As well as the presence and relationship of cytokines (IL-33, TGF-β, and TNF-α) in the mentioned groups, taking into account that all respondents were in a stable phase of schizophrenia." (PMID 35958655, 2022). "In the present review, we collected interleukin 33 data in main psychiatric disorders such as MDD, BD, schizophrenia, ASD, anxiety, and PTSD." (PMID 33810498, 2021). "A study showed that the serum levels of IL-33 and sST2 were similar between patients with schizophrenia and controls, but there was no significant statistical difference." (PMID 35743957, 2022). "Studies on serum levels of IL-33 in patients with schizophrenia and healthy individuals have not yielded consistent results." (PMID 35743957, 2022). "Moreover, serum levels of IL-33 and soluble ST2 positively correlate with cognitive performance in schizophrenia patients." (PMID 32393354, 2020). "We have shown here that the level of IL-33 is not significantly altered in schizophrenia patients in remission." (PMID 29988422, 2018). "Therefore, in this study we have investigated the serum level of Gal-3, IL-33 and soluble ST2 (sST2) in different stages of schizophrenia." (PMID 29988422, 2018).
gout (15 papers, 2015 to 2025). A condition characterized by painful swelling of the joints, which is caused by deposition of urate crystals. "We next explored the mechanisms underlying how IL-33/ST2 mediates the pain response of mouse gout model." (PMID 33204337, 2020). "In conclusion, our data provide clear evidences that the increased expression of IL-33 in the gout patients might be due to a cause of self-negative regulation, which inhibits the development of MSU-induced inflammation through expanding MDSCs." (PMID 30863362, 2019). "Overexpression of IL-33 abolished the anti-inflammatory effects of auranofin, highlighting the central role of IL-33 in gout pathogenesis." (PMID 41090769, 2025). "Together, our findings suggest that auranofin alleviates MSU-induced inflammation by concurrently inhibiting NLRP3 inflammasome activation and IL-33-mediated neutrophil recruitment, supporting its potential as a dual-action therapeutic candidate for gout." (PMID 41090769, 2025). "IL-33 not only triggers macrophage to release IL-1β, enhancing inflammation and pain; in gouty arthritis, it but also modulates bone cancer pain by regulating IL-6 and IL-1β." (PMID 36287299, 2022). "It was reported that higher levels of IL-33 and neutrophil counts were detected in joint synovial fluid in patients with gout than those in osteoarthritis." (PMID 34589505, 2021). "We further examined the effect of in vivo macrophages depletion using clodronate-containing liposomes on IL-33 release in gout." (PMID 33204337, 2020). "Nonetheless, the exact cellular interactions that IL-33/ST2 mediated to promote neutrophil influx under gout condition remain to be further studied." (PMID 33204337, 2020). "Consistently, TNFα and IL-lβ also induced the up-regulation of IL-33 expression in the synovial fibroblasts from gout patients." (PMID 30863362, 2019). "Next, we sought to determine the role of increased expression of IL-33 in gout by using MSU-induced peritonitis experimental model." (PMID 30863362, 2019). "Here, we also observed an increased production of IL-33 in fibroblasts from gout patients, which were stimulated by inflammatory cytokines or MSU." (PMID 30863362, 2019). "In this study, an increased IL-33 expression was observed in gout patients, which was positively correlated with inflammatory marker CRP." (PMID 30863362, 2019). "Specially, the increased number of MDSCs induced by IL-33 in the animal gout model was characterized by surface markers CD11b+Gr-1intF4/80+." (PMID 30863362, 2019). "The serum IL-33 expression is predominantly increased in gout patients compared to healthy controls and positively correlated with the expression of HDL, while negatively correlated with LDL expression." (PMID 30761089, 2019). "It has been reported that the elevated IL-33 level is considerably reduced in renal impairment when compared with normal renal function in gout patients." (PMID 30761089, 2019). "In this study, we recruited more participants to compare levels of IL-33 in gout patients and healthy volunteers." (PMID 30863362, 2019). "Therefore, we speculate that an increased expression of IL-33 in the gout patients might be due to a cause of self-negative regulation, while the increased amount of IL-33 expression was inadequate to induce a potent protective effect to reduce the development of gout." (PMID 30863362, 2019). "As expected, the expression of IL-1β was significantly decreased in the gout model mice with IL-33 treatment." (PMID 30863362, 2019). "In this study, we found an increased level of IL-33 in gout patients, which was positively correlated with inflammatory marker CRP." (PMID 30863362, 2019). "In our study, we found that the expression of IL-33 in gout patients was significantly higher than that of the healthy control group, which was positively correlated with inflammatory indicator C-reactive protein (CRP)." (PMID 30863362, 2019).
gout (continued). "Although a protective role of IL-33 in the kidney injury of gout was observed, we here found a positive correlation between the increased IL-33 expression and inflammatory indicator CRP (r = 0.38, p = 0.005)." (PMID 30863362, 2019). "We found that serum levels of IL-33 in gout patients were significantly higher than healthy subjects." (PMID 27579324, 2016). "Currently, compared with healthy controls, the serum IL-33 levels in gout patients were significantly increased (p < 0.0001)." (PMID 27579324, 2016). "Serum IL-33 levels were significantly elevated in patients with gout patients when compared with healthy control subjects." (PMID 27579324, 2016). "In line with above results, we also observed that serum levels of IL-33 were positively correlated with HDL from gout patients, and the expressya ion of IL-33 was markedly high in the patient without kidney damage." (PMID 27579324, 2016). "In the present study, we examine serum levels of IL-33 by ELISA from gout patients, and correlation with clinical markers in patients with gout was analyzed." (PMID 27579324, 2016). "The current study therefore aimed to investigate the associations between the IL-33 rs3939286 A/G, IL-1RL1 rs13015714 G/T, IL-23R rs10889677 A/C, and STAT4 rs7574865 G/T single nucleotide polymorphisms (SNPs) and the risk of gout." (PMID 26399911, 2015). "We therefore propose IL-33, IL-1RL1, IL-23R, and STAT4 as potential candidate susceptibility genes for gout." (PMID 26399911, 2015). "It was also found that macrophages in gout could produce IL-33 and increase CXCL1, CCL 3, and IL-1β through an autocrine pattern." (PMID 34589505, 2021). "Targeting IL-33/ST2 may represent a novel therapeutic approach to ameliorate gout pain and inflammation." (PMID 33204337, 2020). "We then studied the behavioral effects of exogenously injecting IL-33 into gout model mice." (PMID 33204337, 2020). "Furthermore, three groups of cells induced by IL-33 were isolated and adoptively transferred to the gout model mice." (PMID 30863362, 2019). "However, exogenous recombinant IL-33 significantly ameliorated the development of animal gout model." (PMID 30863362, 2019). "This is the first to document the role of IL-33 in a mouse model of human gout." (PMID 30863362, 2019). "In conclusion, our data provide clear evidences that the increased expression of IL-33 in gout patients was involved in the self-resolution of MSU-induced inflammation, and IL-33 might be a promising therapeutic target for gout." (PMID 30863362, 2019). "Our previous study demonstrated that IL-33 might play a protective role in kidney injury in gout patients by regulating the lipid metabolism." (PMID 30863362, 2019). "Our previous study has shown that the serum IL-33 level was predominantly increased in gout patients when compared to healthy controls, and the increased IL-33 expression might play a protective role in kidney injury by regulating lipid metabolism in gout." (PMID 30863362, 2019). "Besides, the inflammatory cytokine IL-6 was also inhibited by IL-33 treatment in the gout animal model." (PMID 30863362, 2019). "We speculate that IL-33-induced MDSCs might alleviate the development of gout inflammation through phagocytosing neutrophils." (PMID 30863362, 2019). "In this study, we investigated the potential role of IL-33 in gout patients." (PMID 27579324, 2016). "In the present study, we demonstrated the IL-33 expression and its potential role in gout patients." (PMID 27579324, 2016). "Furthermore, the elevated IL-33 levels were considerably reduced in renal impairment when compared with normal renal function in gout patients." (PMID 27579324, 2016). "In conclusion, the results presented here suggest that the serum IL-33 could be a sensitive marker for kidney function in gout patients." (PMID 27579324, 2016).